IL5 (interleukin 5)
Diseases named in the same sentence as IL5 in open-access papers (continued):
Sharing a sentence is not in itself a finding about the gene and the disease.
asthma (continued). "As a Th2-driven inflammatory response, asthma is characterized by increase in the levels of IL-4, IL-5, IL-13, and GM-CSF along with an increase in the level of TNF-α and TGF-β in BALF and serum, which primarily act as pro-inflammatory cytokines." (PMID 30619345, 2018). "In the pathogenesis of asthma, the Th2 and Th17 lymphocytes in the adaptive immune system can produce cytokines (such as IL-5, IL-13, and IL-17) to control disease." (PMID 30761008, 2018). "A study of experimental RV infection in asthma showed that virus-induced IL-33 release correlated with high IL-5 and IL-13 concentrations in the airway." (PMID 30174671, 2018). "Serum IL-4, IL-5, IL-10, adhesion molecules and sE-selectin are all involved in the pathogenesis of allergic rhinitis and asthma, which can be used to evaluate the degrees of respiratory allergic diseases." (PMID 30344593, 2018). "Due to its ability to activate Th2 and dendritic cells, IL-33 plays an important role in initiating allergic inflammation and asthma by producing Th2 cytokines including IL-5 and IL-13." (PMID 29540228, 2018). "Once a large amount of EOS accumulated at the antigen-stimulating site, IL-5, together with other factors, causes the EOS to prolong survival and release a range of protein particles, leading to asthma attacks." (PMID 29713367, 2018). "Anti-IL-5 therapy leads to significant increase in lung function, oxygenation, QoL and asthma control." (PMID 30021546, 2018). "Patients who travel regularly or who reside in countries where helminths are endemic should be followed carefully now that anti-IL-5 treatment is widely available for severe asthma." (PMID 29682504, 2018). "Stratification of patients with severe asthma by blood eosinophil counts predicts responders to anti-interleukin (IL)-5 (mepolizumab and reslizumab) and anti-IL-5 receptor α (benralizumab) therapies." (PMID 29713354, 2018). "In asthma, Th2-related cytokines such as IL-4, IL-5, and IL-13 significantly increase; the development of antibodies against Th2-related cytokines is an active field of research." (PMID 29151835, 2017). "Inhalation of an ASO targeting Mex-3B suppressed airway eosinophilia, lung inflammation, mucus hypersecretion, and BAL fluid levels of Th2 cytokine IL-4, IL-5 and IL-13 in an experimental model of asthma." (PMID 28106744, 2017). "The eosinophilia observed in asthma and allergic diseases is partially controlled by the Th2 cytokine IL-5." (PMID 28721208, 2017). "Levels of IL-3, IL-4, and IL-5 correlated well with the eosinophil counts in tissue in asthma with CRS." (PMID 28199345, 2017). "This gene set includes numerous cytokines that mediate Th2 cell signaling associated with asthma (IL3, IL4, IL5, IL9, IL10 and IL13), as well as components of the IgE receptor (FCERA, FCERG, MS4A2) and eosinophil granule proteins (ECP, EDN, EPX, and MBP)." (PMID 28854632, 2017). "Among the different members of Th2 cytokines family, IL-4, IL-5, and IL-13 contribute primarily in asthma." (PMID 28974953, 2017). "The Th2-derived cytokines, IL-4, IL-5, IL-9, and IL-13 mRNA expression was also markedly increased in the patients with severe asthma patients with CRS." (PMID 28199345, 2017). "Th2 lymphocytes play a critical role in the initiation and progression of allergic diseases, including atopic dermatitis and asthma, by releasing IL-4, IL-5, and IL-13." (PMID 29062168, 2017). "IL-13 exacerbates IL-5-triggered asthma, and overexpression of IL-13 in the intestinal tract induces inflammatory bowel disease and causes lesions of the endothelium, which eventually lead to arteriosclerosis and other cardiovascular dysfunctions." (PMID 29292401, 2017). "Overproduction of Th2 cytokines, such as IL-4 and IL-5 which are released by Th2 cells, is shown to contribute to the pathophysiology of asthma." (PMID 28623898, 2017). "A lentivirus-delivered IL-5 siRNA was found to moderate cell infiltration as well as AHR in a mouse asthma model." (PMID 28106744, 2017).
asthma (continued). "Both current asthma at 16.5 years and ever wheeze at 16.5 years were negatively associated with methylation levels at IL5RA, a gene encoding alpha subunit of the interleukin-5 (IL5) receptor." (PMID 29046734, 2017). "Additional control of Th2 inflammation can be achieved in select asthma patients with biologic therapies such as anti-IL-5 and anti-IL-13 antibodies, which have also been trialed in EoE." (PMID 28831387, 2017). "Asthma is characterized by type 2 immune responses and production of cytokines such as IL-4, IL-5 and IL-13 that drive the allergic disease." (PMID 28830530, 2017). "IL-5 (major cytokine responsible for eosinophilic infiltration in asthma) was found to be higher in BALF and lung homogenate of OVA-treated mice as compared to control mice." (PMID 28293189, 2017). "Mepolizumab and reslizumab, anti-IL-5 monoclonal antibodies, have recently been approved for asthma therapy." (PMID 28855973, 2017). "Monoclonal antibodies directed against IgE, IL-4 and 13 and IL-5 have been extensively studied in asthma, and one anti-IgE and two anti-IL-5 monoclonal antibodies have been approved by the US FDA for the treatment of severe asthma." (PMID 28855973, 2017). "Th2 cytokines (IL-4, IL-5, and IL-13) are known to be critically involved in the pathogenesis of asthma." (PMID 28746467, 2017). "The roles of IL-5 in the pathogenesis of asthma and allergic diseases have been extensively investigated." (PMID 28317868, 2017). "OVA-IgE, IL-4, IL-5, IL-13 and INF-gamma in BALF was also increased in TLR2-deficient mice treated with B7-H3, which suggest in OVA-induced asthma model B7-H3 augment the inflammatory response independent of TLR2 pathway." (PMID 28094276, 2017). "In patients with asthma, Th2 cells release elevated IL-5 levels, which increase eosinophil differentiation in bone marrow cells." (PMID 28243240, 2017). "In that regard, recent asthma treatments have been focusing on blocking Type 2 cytokines, notably IL-4, IL-5, and IL-13." (PMID 28848734, 2017). "Multiple cell types, including mast cells, eosinophils, basophils, neutrophils, and Th2 lymphocytes, contribute to the pathogenesis of asthma by producing cytokines like interleukin- (IL-) 4, IL-5, and IL-13." (PMID 29062168, 2017). "CD4+ T helper cells play an important role in the pathogenesis of asthma by secreting IL-4, IL-5 and IL-1326." (PMID 28240301, 2017). "Beyond blocking IL-5, blocking the IL-5 receptor has also been an important therapeutic target against asthma." (PMID 28721208, 2017). "Further, NGF stimulation of human pDCs from patients with asthma aggravated allergen-specific T cell proliferation and IL-5 secretion." (PMID 28516419, 2017). "In fact, IL-5 exerts selective action on eosinophils, which, in turn, sustain airway inflammation and worsen asthma symptoms and control." (PMID 28913336, 2017). "Asthma is a Th-2 cell mediated disease, the elevated levels of IL-5 and IL-6 were seen in OVA-treated mice." (PMID 28293189, 2017). "This common subtype of asthma is characterized by the release of signature cytokines interleukin (IL)-4, IL-5, and IL-13 from cells of both the innate and the adaptive immune systems." (PMID 28721208, 2017). "The increased percentage of eosinophils in sputum and elevated AHR in asthma are correlated with IL-5 secretion." (PMID 28570692, 2017). "Mixed responses characterized by TH2 (IL-5) and TH17-associated cytokines were associated with Difficult-to-Control asthma." (PMID 28686637, 2017). "Arguably, the best evidence for the role of IL-5 in human asthma is the success of humanized, monoclonal anti-IL-5 antibodies in treating eosinophilic asthma although their ability to decrease remodeling in human tissues is not clear." (PMID 28831387, 2017). "Compared with the asthma model group, the serum levels of IL-4, IL-5 and IgE in each group of drug administration was remarkably decreased (P < 0.01)." (PMID 28764781, 2017).
asthma (continued). "In particular, nasal IL-5 and IL-13 are upregulated in asthma versus controls, especially on days 3–5, and this confirms the greater induction demonstrated in terms of changes from baseline in asthmatic compare to healthy subjects." (PMID 28373098, 2017). "Of particular importance for the proposed link between RSV and asthma, IL-5 was markedly reduced in RRR compared to CRR weanlings during recurrent postnatal rrRSV LRTI (360.6 ± 55.77 pg/ml vs. 488.1 ± 17.92 pg/ml; P˂0.05)." (PMID 28178290, 2017). "To date, the only two biologics that are FDA-approved and being used to treat asthma are the humanized monoclonal IgE-targeting antibody omalizumab (Xolair) and the humanized monoclonal IL-5-targeting antibody mepolizumab (Nucala)." (PMID 27378934, 2016). "TLR7 stimulation suppresses eosinophilic airway inflammation in a variety of animal models of asthma through reducing Th2 cytokines such as IL-4 and IL-5 as well as eotaxin in the lung and IgE." (PMID 27274620, 2016). "Two different humanized anti-IL-5 monoclonal antibodies (mepolizumab and reslizumab) have been proven effective and safe in severe asthma, in patients with more severe eosinophilic inflammation." (PMID 27942351, 2016). "At least one therapy, mepolizumab (anti-IL-5), is effective for reducing asthma exacerbations in patients with eosinophilic asthma, yet does not appear to affect early/late asthmatic responses during allergen challenge." (PMID 26993628, 2016). "ELISA analysis showed that picroside II down-regulated the levels of Th2-related cytokines (including IL-4, IL-5, and IL-13) and asthma-related mediators, but it up-regulated Th1-related cytokine, IFNγ in BALF." (PMID 27870920, 2016). "The aim of the present review is to provide an overview of the evidence behind the use of anti-IgE and anti-IL-5 in severe asthma and possibly to assess the clinician's judgment in choosing the right treatment for the right patient." (PMID 27834175, 2016). "We identified 20 RCTs investigating the effect of anti-interleukin 5 monoclonal antibodies in patients with asthma." (PMID 27875559, 2016). "Anti-IgE (omalizumab) and anti-IL-5 (mepolizumab) antibodies are biological agents that interfere in different steps of the Th2 inflammatory cascade and are licensed in severe asthma." (PMID 27834175, 2016). "The OVA-induced airway hypersensitivity model of asthma used here results in eosinophilic inflammation in the lung, pulmonary production of Th2 cytokines (IL-4, IL-5 and IL-13) and serum IgE production." (PMID 27390655, 2016). "Subgroup analyses showed the efficacy of anti-interleukin 5 on asthma exacerbations were only influenced by asthma severity." (PMID 27875559, 2016). "Reduction of eosinophils by application of anti-IL-5 mAbs ameliorated asthma in a selected sub-population of asthma patients with demonstrable eosinophilic airway inflammation (references in Walsh et. al.)." (PMID 27442134, 2016). "As it is known, inflammatory mediators, such as Th2 cells, producing IL-4, IL-5 and IL-13 contribute to not only inflammation but also airway remodeling in asthma." (PMID 27590515, 2016). "Since IL-5 is essential for eosinophil maturation and eosinophils are important in asthma, animal and human studies showed that eosinophilia in blood and BALF can be reduced with monoclonal antibodies against IL-5." (PMID 26003185, 2016). "Patients with this profile are the commonest participants included in recent asthma studies for novel T2-inflammation focused therapeutics, e.g. anti-IL-13 and anti- IL-5 monoclonal antibodies." (PMID 27978840, 2016). "Further, considering the inflammatory mediators involved in asthma, kuwanon G significantly decreased the levels of IL-4, IL-5, and IL-13 in the sera and in bronchoalveolar lavage of asthma mice." (PMID 27445433, 2016).
asthma (continued). "To investigate the anti-asthmatic effects of picroside II, we determined the levels of inflammatory cytokines, such as Th1 cytokine (IFNγ), Th2 cytokines (IL-4, IL-5, and IL-13), and asthma related cytokine (IL-33) in the BALF using ELISA kit." (PMID 27870920, 2016). "Anti-IgE hMabs are effective in severe allergic asthma and hMabs directed against IL-5 in severe eosinophilic asthma, particularly in reducing severe asthma exacerbations." (PMID 27942351, 2016). "Anti-IL-5 antibodies inhibit the action of IL-5, which has an important role in the pathogenesis of asthma by damaging tissue due to eosinophil accumulation during pulmonary inflammation." (PMID 27053925, 2016). "Our data demonstrating reduced IL-4 and IL-5 levels in WGP-treated mice in an OVA-induced asthma model is in agreement with these findings." (PMID 27390655, 2016). "The ideal study population for the evaluation of anti-IL-5 treatment would be a population of asthmatic patients with poorly controlled asthma, with high numbers of airway eosinophils and who are already under treatment with ICS." (PMID 27834175, 2016). "The authors state that IL-33 induction directly correlates with viral load and IL-5 and IL-13 levels, proposing IL-33 inhibition as a novel therapeutic approach for virus-induced asthma exacerbations." (PMID 27334012, 2016). "When GFBB was used in patients suffering from HDM-induced allergy and asthma, the peak expiratory flow was increased and the production of systemic Th2 cytokines (IL-4, IL-5 and IL-13) was reduced." (PMID 26003185, 2016). "IL-5 knockout mice appeared to confirm a role in asthma models in which eosinophilia and AHR are markedly suppressed." (PMID 26334389, 2016). "The anti-IL-5 agents benralizumab, reslizumab, and mepolizumab have been investigated for treating asthma." (PMID 27875559, 2016). "Recently, we found that maternal serum and breast milk whey levels of IL-5 and IL-13 are risk markers for asthma-like symptoms among children; whereas whey IgA and TGF-β1 were protective by diminishing the relative risk of asthma-like symptoms." (PMID 27222655, 2016). "RAO shares many features with human asthma, including an increased number of cells expressing mRNA for interleukin (IL)-4 and IL-5 and a decreased expression of IFN-γ in bronchoalveolar lavage fluid (BALF) of affected horses." (PMID 27651133, 2016). "Given the relationship of IL-5 to eosinophilia and asthma severity, human(ized) monoclonal antibodies targeting IL-5 have shown great promise in severe refractory asthma with persistent eosinophilia." (PMID 27875559, 2016). "Mepolizumab, an interleukin-5 (IL-5) antibody, substantially reduced asthma exacerbations in human patients with eosinophilic asthma." (PMID 27657144, 2016). "In a multivariate analysis, atopy was broadly related to increased Th2‐like responses to all antigens and PHA, while asthma was only weakly related to mitogen‐induced IL‐4 and IL‐5 responses." (PMID 27042305, 2016). "The therapeutic use in severe asthma of antibodies targeting IL-5 is supported by abundant data from in vitro experiments, animal models and clinical trials." (PMID 27117585, 2016). "In human, rhinovirus infection induced asthma exacerbation dependent of IL-33 and the production of type 2 cytokines IL-4, IL-5, and IL-13." (PMID 27334012, 2016). "A dominant Th2 response induces several characteristic features of asthma, including eosinophil recruitment, overproduction of Th2-type cytokines (such as IL-4, IL-5, and IL-13), and elevation in the level of IgE." (PMID 27741312, 2016). "Targeted therapies at IgE, interleukin-4 (IL-4), IL-4 receptor, IL-5, IL-13, tumor necrosis factor-α, and CRTh2 are new treatment paradigms for asthma." (PMID 27274620, 2016). "A wealth of inflammatory mediators, particularly the Th2-associated cytokines IL-4, IL-5, and IL-13, and the pro-inflammatory mediator TNF-α, contributed substantially to airway inflammation in asthma." (PMID 26343632, 2015).
asthma (continued). "Previous studies in humans have shown that the addition of anti-IL-5 monoclonal antibody on asthma therapy significantly accelerated apoptosis of eosinophils, thereby decreasing pulmonary eosinophilia." (PMID 25890178, 2015). "Various studies have shown that Th type 1 (Th1)-related cytokines (interleukin [IL]-12 and IFN-γ), Th type 2 (Th2)-related cytokines (IL-4, IL-5, and IL-13), and proinflammatory cytokines (IL-1β, IL-6, and TNF-α) are associated with asthma." (PMID 25658604, 2015). "We determined the levels of 6 cytokines implicated in asthma, which can be divided by the response profiles Th1 (TNF-α and IL-6) and Th2 (IL-4, IL-13, IL-10, and IL-5)." (PMID 26101464, 2015). "Representing heterogeneous entities, in the most phenotype of asthma, type 2 immune responses are up-regulated with elevated levels of IL-4, IL-5, IL-13 and GM-CSF, whereas also pro-inflammatory TH1 cytokines and adipokines have been found elevated." (PMID 25781614, 2015). "Intriguingly, we observed that asthma mice treated with CaeA exhibited significant reduction in IL-5 and IL-13 levels in the BALF, as well as in the lungs." (PMID 26481184, 2015). "These alterations are accompanied by changes in biological markers such as cytokines (IL-4 or IL-5) and allergen-specific IgE, which are crucial mediators in the development of asthma." (PMID 26588845, 2015). "Children in Class 5 (all of whom produced high levels of IL‐13, and almost all produced high levels of IL‐5, with some production of IL‐10 and IFN‐γ) had a fivefold increase in the risk of asthma." (PMID 26061524, 2015). "It should be noted that we stained only for IL-13, and therefore we cannot exclude an increase in TH2 cells secreting IL-4 or IL-5 in the more severe asthma clusters." (PMID 25746968, 2015). "Further, decline in the levels of IL-4, IL-5 and IL-13 cytokines and IgE was noted in the animals suffering from asthma." (PMID 26481184, 2015). "When CD4+ T cells from asthma patients were stimulated with dust mite allergen in the presence of calcitriol, the hormone decreased IL-5, IL-9, and IL-13 production." (PMID 25852682, 2015). "Patients with mild-to-moderate asthma present with elevated levels of IL-4 and IL-5 in BAL fluid, and pulmonary isolates found elevated numbers of CD4+ T cells and a high degree of airway eosinophilia." (PMID 26346739, 2015). "All these were associated to a Th2-type cytokine profile (with the production of IL-5, IL-13 and IL-4), which is important for the development and maintenance of the Th2 response characteristic of asthma." (PMID 25890178, 2015). "Eosinophil apoptosis is induced by lipoxin A4, an arachidonic acid metabolite that inhibits IL-5 production and whose levels have been found to be decreased in the exhaled breath condensate of patients with asthma undergoing disease exacerbations." (PMID 25878402, 2015). "In sharp contrast, B7-H3 KO mice developed severe ovalbumin (OVA)-induced asthma with characteristic infiltrations of eosinophils in the lung, increased IL-5 and IL-13 in lavage fluid, and elevated IgE anti-OVA antibodies in the blood." (PMID 26065426, 2015). "With the exception of IL-12, the mRNA levels of asthma-related cytokines were suppressed, and the mRNA expression of IL-4 and IL-5 was almost completely inhibited." (PMID 25658604, 2015). "The Th2 cytokines IL-4, IL-5, and IL-13 are the major cytokines for development of atopic diseases, such as asthma, rhinitis, and dermatitis." (PMID 26064160, 2015). "The values of IL-5 in patients with asthma were significantly decreased after treatment with corticosteroids." (PMID 27275299, 2015). "In our previous studies using murine models of asthma, the recovery of IL-4, IL-5 and IL-13 in bronchoalveolar lavage (BAL) fluid from female mice was significantly higher than that of male mice." (PMID 26488300, 2015).